CCL2 (C-C motif chemokine ligand 2)
Diseases named in the same sentence as CCL2 in open-access papers (continued):
Sharing a sentence is not in itself a finding about the gene and the disease.
prostate carcinoma (continued). "In addition to CCL2, the C.M. collected from MSCs with the downregulation of IL1RN by the siRNA approach exhibited anti-proliferation activity against the prostate cancer cells." (PMID 36672395, 2023). "For example, treatment with the anti-CCL2 monoclonal antibody Carlumab in patients with prostate cancer does not have a long-lasting effect." (PMID 35999359, 2023). "Furthermore, there is evidence that nitration of proteins such as CCL2 and LCK decreases the number of tumour-infiltrating T cells in colon cancer and it skews them towards an unresponsive phenotype in prostate cancer." (PMID 35660630, 2022). "Despite promising efficacy of a CCL2 mAb in rodent models of prostate cancer, sustained suppression of serum CCL2 concentrations was not achieved in patients with mCRPC." (PMID 36258057, 2022). "The anti-CCL2 monoclonal antibody carlumab failed to inhibit tumor growth in early-stage clinical trials in prostate cancer as it was unable to sustain CCL2 blockade due to induction of compensatory mechanisms." (PMID 34803925, 2021). "We compared the expression levels of eight integrin subunits (ITGA2, ITGA5, ITGAV, ITGB1, ITGB3, ITGB4, ITGB5, and ITGB6), HOXB13, HOXA11-AS, CCL2, CXCL12, and IBSP in prostate cancer tissues that had metastasized to bone, lymph nodes, lungs, liver, and other organs." (PMID 33514011, 2021). "The SAM pointed domain-containing ETS transcription factor (E26 transcription factor) is expressed in prostate cancer that is regulated by AR signaling and has a negative correlation with CCL2." (PMID 34445235, 2021). "An antibody against CCL2 (CNTO888, Carlumab), investigated in patients with metastatic castration-resistant prostate cancer and patients with solid tumors, or an antibody against CCR2 (MLN1202, Plozalizumab), investigated in patients with RA, was not successful in clinical trials to date." (PMID 33540898, 2021). "Furthermore, overexpression of the monocyte chemoattractant protein-1 (MCP-1, also known as CC chemokine ligand 2/CCL2 which is the ligand for CCR2) in human prostate cancer cells increases macrophage accumulation and enhances bone metastasis." (PMID 34803925, 2021). "The anti-CCL2 monoclonal antibody carlumab failed to inhibit tumor growth in early stage clinical trials in prostate cancer, since CCL2 levels increased just one week after the treatment through the induction of compensatory mechanisms." (PMID 32708142, 2020). "It was reported that CCL2-positive prostate cancer tissues have more macrophage infiltration than CCL2-negative cancer tissues, CCL2 can also promote prostate cancer progression indirectly by increasing the recruitment of TAMs into the tumor microenvironment." (PMID 33297571, 2020). "A single-cell RNA sequencing study conducted in prostate cancer demonstrated that different clusters of CAFs secreted various levels of proinflammatory cytokines such as CXCL12 and CCL2, highlighting that several CAF subpopulations may interact with MDSCs." (PMID 33066357, 2020). "Similarly, the inflammatory chemokine CCL2 was found to be upregulated in prostate cancer patients treated with DTX and in in vitro models of prostate cancer treated with DTX." (PMID 33182737, 2020). "We observed the increased expression of CXCL8, CCL2, CXCL10, and CCL20 in prostate cancer tissues induced by intraprostatic injection of LNCaP cells stably transfected with SFMBT2 shRNA compared with prostate tissues injected with LNCaP cells stably transfected with control shRNA." (PMID 32971847, 2020). "Also, the expression level of CXCL8, CCL2, CXCL10, and CCL20 was proportionally related to a high Gleason score of ≥8, which seems closely related to prostate cancer invasion and metastasis." (PMID 32971847, 2020). "For instance, polycomb repressive complex 1 (PRC1) promotes metastasis of double negative [androgen receptor (AR) and neuroendocrine] prostate cancers by CCL2 expression, which regulates TAM self-renewal and recruitment." (PMID 32971847, 2020).
prostate carcinoma (continued). "Carlumab (CNTO 888), a human monoclonal anti-CCL2 antibody, was well-tolerated but did not block the CCL2/CCR2 axis or show antitumor activity as a single agent in metastatic castration-resistant prostate cancer." (PMID 30871117, 2019). "Notably, addition of CCL2 induced both CCL22 and CCR4 expression in prostate cancer cells; CCL22 subsequently promoted the migration and invasion of prostate cancer cells in an autocrine manner, via enhanced phosphorylation of Akt." (PMID 30871130, 2019). "The CCL2/CCR2 axis between cancer cells and MAMs may also promote bone metastasis of prostate cancer by supporting the activation of osteoclasts." (PMID 29594035, 2018). "The addition of CCL2 induced CCL22 and CCR4 production in prostate cancer cells." (PMID 28039457, 2017). "Previous studies have reported that a combination of STAT3, CCL2, and EMT activates prostate cancer progression and may provide a novel therapeutic target for the prevention of prostate cancer metastasis." (PMID 28157698, 2017). "Interestingly, CCL2 treatment resulted in significant increases in CCR2 and CCR4 protein levels in prostate cancer cells and promoted recruitment of monocytes into the tumor microenvironment, where they differentiated into TAMs." (PMID 28039457, 2017). "For instance, CCL2 has been reported to be present in the microenvironment of many types of cancers, and CCR2 has been demonstrated to be upregulated in cancer cells, including prostate cancer cells." (PMID 28039457, 2017). "Additionally, neutralizing antibodies against CCL2 (anti-human CNTO888 and anti-mouse C1142) in combination with docetaxel diminish prostate cancer cell–mediated tumor burden and induce tumor regression." (PMID 28467800, 2017). "Our results demonstrated that DT could reduce the secretion of chemokines, including CCL2, CCL5, and ICAM-1, in prostate cancer cells, and inhibit prostate cancer cell migration under the macrophages’ cultured medium." (PMID 28157698, 2017). "The novel classification using CCL2 and PSA levels together may serve as a useful tool to improve prediction of survival and the efficacy of ADT in patients with prostate cancer." (PMID 26701731, 2016). "The level of CCL2 in patients with prostate cancer was significantly higher than those without prostate cancer in all PSA ranges ( < 41, < 20, < 10, 4-41, 4-20, and 4-10 ng/mL)." (PMID 26701731, 2016). "To determine the in vitro effects of CCL2 stimulation on prostate cancer cell migration without androgen deprivation, we used a transwell migration assay." (PMID 26701731, 2016). "The other DEGs with prognostic significance in prostate cancer that were not differentially expressed in our list of DEGs include IL-7, CCL-2, and CDH1." (PMID 26683658, 2015). "Prostate cancer proliferation and metastasis may also be stimulated by SDF-1 (CXCL12), CCL2 and other factors." (PMID 26317041, 2015). "Our initial data suggests that stromal rather than prostate cancer cells are the principal source of CCL2 and CXCL12." (PMID 24970800, 2014). "Conversely, modulation of this tumor suppressor gene had no impact on the expression of either CCL2 or CXCL12 in prostate cancer cells." (PMID 24970800, 2014). "Additionally, prostate cancers typically express high levels of pro-inflammatory chemokines, including CXCL12 (SDF-1), CCL5 (RANTES), and CCL2 (MCP-1)." (PMID 23362217, 2013). "Intriguingly, non-hematological epithelial malignancies, such as prostate cancer, have been found to be addicted to CCL2 for their survival and malignant behaviour." (PMID 21943176, 2011). "They found that prostate cancer cells highly express and secrete GDF-15, which further induces the expression of osteoclastogenesis-related genes in osteoclasts and the expression of chemoattractant protein-1 (MCP-1/CCL2), which is involved in macrophage recruitment to osteoblasts in mice." (PMID 39000420, 2024).
prostate carcinoma (continued). "Additionally, when CXCR2 expression is increased in prostate cancer cells, the expression of secretory factors such as VEGF, angiogenin, thrombopoietin, oncostatin M, IGF-1, CCL2/MCP-1, CCL22/MDC, and M-CSF is increased, namely factors that are involved in tumorigenesis." (PMID 37108425, 2023). "In prostate cancer (PRAD) cells, the expression of CCR2 (the receptor of CCL2) promotes NI, and the expression of CCR2 is closely related to the activity of MAPK and Akt pathways and the migration of cancer cells to chemokine (C-C motif) ligand 2 (CCL2) and DRG." (PMID 36900158, 2023). "However, in metastatic castration-resistant prostate cancer, carlumab, a human monoclonal antibody against CCL2, did not produce a therapeutic effect (NCT00992186)." (PMID 36241867, 2022). "Moreover, CCL2 could promote the survival and proliferation of THP-1, prostate cancer cell line PC3, renal cell carcinoma cell line 786-O and KAKI-1, and lung cancer cell line A549." (PMID 35726234, 2022). "In the bone marrow milieu, C-C motif chemokine ligand 2 (CCL2; also known as monocyte chemoattractant protein 1), the primary ligand for C-C motif chemokine receptor 2 (CCR2), is produced in bone marrow osteoblasts, endothelial cells, stromal cells, and prostate cancer cells." (PMID 33514011, 2021). "In addition, expression of CXCL8, CCL2, CXCL10, and CCL20 was also increased in prostate cancer tissue induced by intraprostatic injection of LNCaP cells stably transfected with SFMBT2 shRNA and in the tissue of prostate cancer patients." (PMID 32971847, 2020). "Here we reviewed recent findings, which link CCL2/CCR2 to the inflammation and cancer pathogenesis, and discussed the therapeutic potential of CCL2/CCR2 axis in cancer treatment based on results from our group and other investigators, with a major focus on prostate cancer." (PMID 32471499, 2020). "In summary, CCL2 and CCL22 secretion in the prostate cancer tumor microenvironment may induce not only direct metastasis of prostate cancer cells, but also promote the activation of TAMs and Tregs, which facilitate a suitable environment for cancer progression." (PMID 30871130, 2019). "Scholars have argued that the CCL2–p-STAT3 pathway stimulates prostate cancer metastasis and progression, and may be critical in future efforts to develop new therapeutic approaches for treating prostate cancer." (PMID 28157698, 2017). "However, our present study shows a significant difference in CCL2 levels alone between men with and without prostate cancer." (PMID 26701731, 2016). "Importantly, we found that CCL2 levels were significantly different between men (n = 379) with and without prostate cancer." (PMID 26701731, 2016). "However, there was a statistically significant difference in CCL2 levels between men with and without prostate cancer (p < 0.0001)." (PMID 26701731, 2016). "CCL2 may serve as well as a predictive biomarker for patients with prostate cancer treated with ADT, suggesting that ADT alone might not be sufficient for patients with prostate cancer with higher CCL2 levels." (PMID 26701731, 2016). "Previous studies have demonstrated that Carlumab (CNTO 888), which is a human IgG1κ monoclonal antibody with high affinity and specificity for human CCL2, does not inhibit the CCL2/CCR2 axis or demonstrate antitumor activity as a single agent in metastatic castration-resistant prostate cancer." (PMID 25695619, 2015). "Interestingly, addition of high levels of CCL2 at 20 and 30 ng/mL did not stimulate prostate cancer cell invasion." (PMID 26317041, 2015). "The mechanisms by which CCL2 may stimulate prostate cancer cell invasion are not known, but CCL2 may increase cancer cell adhesion, migration and proteolysis." (PMID 26317041, 2015).
prostate carcinoma (continued). "Increased expression and activity of CCL2 and CXCL12 has been reported in both the localized prostate cancer and within the microenvironment of bone metastases, while prior work from our own group has confirmed elevated CXCL8 expression in human prostate cancer tissue." (PMID 24970800, 2014). "However, our study also showed that despite an increased level of CCL2 in prostate cancer, circulating CCL2 could not predict disease progression or patient outcome." (PMID 39199567, 2024). "However, neither CCL2 nor CCR2 tissue expression could predict prostate cancer progression, or other clinicopathological parameters including perineural invasion and patient outcome." (PMID 39199567, 2024). "The usefulness of serum CCL2 in prostate cancer patients was supported by a study using the serum samples of 255 and 124 men with and without prostate cancer, respectively, which reported that serum CCL2 levels in men with prostate cancer were significantly higher than those without." (PMID 33297571, 2020). "However, it remains unclear whether CCL2 promotes prostate cancer progression in prostate cancer cells regardless of therapeutic targeting of androgen/AR signaling." (PMID 26701731, 2016). "Moreover, CCL2 may serve as a prognosticator for prostate cancer patients regardless of their disease status." (PMID 26701731, 2016). "Thus, the production of CCL2 may be mediated by paracrine interactions between the tumor cells and the microenvironment, rather than autocrine production of CCL2 by the C4-2 prostate cancer tumor cells." (PMID 26327448, 2015). "In conclusion, this study shows that although CCL2 and CCR2 are expressed in prostate cancer, with an increased level of CCL2 in the serum, neither CCL2 nor CCR2 expression has a clinical prognostic value in locally advanced prostate cancer." (PMID 39199567, 2024). "Although we did not observe the anti-proliferation effects of the CCL2 KO MSCs in vitro, we sought to examine their roles in the TME developed in an immune-competent syngeneic mouse prostate cancer model." (PMID 36672395, 2023). "Scatter plots of PSA and CCL2 levels showed that men without prostate cancer clustered around a small area of low PSA and CCL2 concentrations, while those of patients with prostate cancer were widely scattered." (PMID 26701731, 2016). "Although MCP-1/CCL2 was produced by both monocytes and prostate cancer cells, it appears that the CCL2 production was not simply driven by a positive feedback loop, since the CCR2 inhibitor RS102895 did not affect the CCL2 levels in the co-cultures." (PMID 26317041, 2015). "Thus, despite experimental data suggesting a role for CCR2 and CCL2 in PNI, in this cohort of locally advanced prostate cancer, we found no significant change in CCR2 or CCL2 protein expression in prostate cancer patients in relation to PNI." (PMID 39199567, 2024). "Furthermore, it has been shown that just docetaxel, not mitoxantrone, induced CCL2 expression in a dose-dependent manner in LNCaP and LAPC4 prostate cancer cell lines." (PMID 36077785, 2022). "Because CCL2 and PSA levels did not correlate, we reasoned that these two useful biomarkers might be a more powerful biomarker profile for prostate cancer when they were combined." (PMID 26701731, 2016). "In addition to the absence of a strong correlation between PSA and CCL2 in patients with prostate cancer, we demonstrated the limitation of PSA alone as a biomarker for prostate cancer." (PMID 26701731, 2016).
colitis (213 papers, 2011 to 2026). Inflammation of the colon. "Genes such as C3, Ccl2, Cxcl1, Ifi44, Lcn2, S100a8, and Tnf were strongly induced during colitis, mirroring previously reported inflammation-associated transcriptional responses." (PMID 40806068, 2025). "Poly(rC)-binding protein 1 (PCBP1) deficiency reduces CCL2 and IL-6 production in colitis macrophages." (PMID 39850880, 2024). "A previous report suggested that blocking the chemokine CCL2, which is known to impede macrophage infiltration, can prevent the development of colitis and colitis-associated carcinogenesis in mice." (PMID 37686390, 2023). "In human and mouse colitis‐associated colorectal cancer models, the expression of CCL2, a TAM marker, increases with neoplastic progression." (PMID 36039642, 2022). "Similar to the findings reported for DSS-induced colitis we show that there is a reduced inflammatory response, associated with a reduction in CCL2 expression, an important immune cell chemoattractant." (PMID 24024606, 2013). "In C57BL/6 mice, the transition from day 7 to 12 was characterised by high diarrhoea scores, increased weight loss, increased macroscopical signs of colitis and peak colon levels of IL-1β, CCL2, CXCL2/3 and CCL4." (PMID 22279558, 2012). "We report that ILK-ko mice are significantly protected from colitis; protection from disease is associated with altered expression of the chemokine, CCL2, and fibronectin." (PMID 21806815, 2011). "Interestingly, it was very recently demonstrated in a pre-clinical experimental model, that the CCL2/NF-κB signaling pathway is implicated in the pathogenesis of colitis and suggested as a therapeutic target." (PMID 36698151, 2023). "In support of the possibility that colitis-associated inflammatory factors contribute to neuroinflammation, we observed increased plasma concentrations of TNFα, MCP-1/CCL2, IL-6, and IFNγ in colitic mice, as well as increased transcription of Tnf, Il1b, and Il6 in their brains." (PMID 34511110, 2021). "The authors also noted increases in CCL2 levels within the colitis-associated CRC and adenomas of patients, suggesting that CCL2 may play a role in human CRC development." (PMID 34298598, 2021). "Collectively, these results demonstrated that CCL2 derived from colon‐resident MSCs is dispensable for either immune cell infiltration or the development of DSS‐induced colitis." (PMID 41309504, 2026). "While our study identifies a critical role for CCL2 derived from BM‐MSCs in our colitis model, our data point to a more sophisticated regulatory network for monocyte recruitment." (PMID 41309504, 2026). "Stress exacerbated disease severity in both infectious (C. rodentium) and chemically induced (DSS) colitis, amplifying colonic expression of Duox2, Nos2, and Ccl2, especially." (PMID 41418891, 2025). "Nobiletin reduces CCL2 expression and collagen deposition in colitis-induced mice, while berberine and geniposide show similar effects in chronic colitis." (PMID 39850880, 2024). "↓ TNF-α, IL-6, CCL2, collagen 3A1, intestinal wall thickness, clinical colitis, tissue damage score, rectal inflammation and bleeding score, mast cell number, and degranulation in the proximal colon." (PMID 39519465, 2024). "That males were more prone to inflammation was corroborated at the systemic level in our study, by a lower baseline IFNγ plasma levels and lower levels of CCL2 during colitis than females." (PMID 39613949, 2024). "The FBXW7/EZH2/CCL2/CCL7 pathway has been shown to exacerbate colitis severity by recruiting CX3CR1 proinflammatory MPhs." (PMID 39568749, 2024). "For example, SARI, commonly used as a colon cancer inhibitor, has been found to increase CCL2 production when deficient, whereas knocking out CCR2 can block this effect, thereby reducing colitis symptoms." (PMID 39850880, 2024). "Bone marrow-derived mesenchymal stromal cells (BM-MSCs) secrete CCL2, influencing colitis development, while IL-10 in MSCs polarizes resident macrophages." (PMID 39850880, 2024).